ICAM1 (intercellular adhesion molecule 1)
Diseases named in the same sentence as ICAM1 in open-access papers (continued):
Sharing a sentence is not in itself a finding about the gene and the disease.
tumor (continued). "Moreover, ICAM-1 expression on tumor cells is critical for CAR T-cell functionality." (PMID 39911389, 2025). "While ICAM-1 was higher in tumor tissue, its systemic relevance remains unclear." (PMID 40652770, 2025). "This implies that CM from the co-culture experiments could upregulate ICAM1 in tumour cells." (PMID 39025845, 2024). "Therefore, it is interesting to speculate that the ICAM1+ rCaps represent favorable sites of tumor cell extravasation and metastasis in the lungs." (PMID 39627185, 2024). "Therefore, ICAM-1 expressed on tumor-infiltrating CD8+ T cells may facilitate their functional activation and tumor-homing ability." (PMID 38169608, 2024). "However, combination with RT, although in vivo ICAM-1 blocking in distant tumors had limited effects on primary tumor growth, significantly diminished the RT-induced systemic antitumor effect in distant tumors compared with that in the RT plus isotype-matched IgG group (P <0.05)." (PMID 38169608, 2024). "Additionally, higher VCAM1 but lower ICAM1 was detected in tumor tissues than in normal tissues." (PMID 38332012, 2024). "Moreover, after insufficient radiofrequency ablation (RFA) for HCC, the upregulation of ICAM-1 in tumor ECs triggers platelet aggregation and activation, leading to increased endothelial permeability through VE-cadherin, and facilitating tumor transendothelial migration." (PMID 38679698, 2024). "Therefore, ICAM-1 plays an important role in tumor immunity, and its in-depth study may be a new hope for TNBC patients." (PMID 38799250, 2024). "Furthermore, the interaction between UM tumor cells and CD8+ T-cells has been associated with poor prognostics and was stronger in BAP1-mutant cells using the activation of ITGB2 (integrin subunit beta 2) and ICAM1 (intercellular adhesion molecule 1)." (PMID 38920653, 2024). "Prompted by the observation that ICAM-1 is more highly expressed in tumor-infiltrating CD8+ T cells than in other immune cell populations 20, we hypothesized that ICAM-1 deficiency impairs the systemic antitumor effect of RT by disrupting antitumor T-cell immunity." (PMID 38169608, 2024). "Moreover, the decreased expression of ICAM-1 with AuNP-P3 could have a dual benefit by minimizing inflammatory responses that may otherwise support tumour growth and reduce the pro-metastatic properties of ICAM-1." (PMID 39682192, 2024). "Noninvasive annotation of the proliferation and effector function of CD8+ T cells by ICAM-1-targeted imaging identified VS-6063, a focal adhesion kinase inhibitor, as a new adjuvant to augment systemic antitumor immunity of RT in an immunologically “cold” tumor model." (PMID 38169608, 2024). "Moreover, our results indicate that ICAM-1 may substitute for CD44 function as a coreceptor of receptor tyrosine kinase MET, and thus may compensate for CD44 loss during other tumor-relevant processes in Nf2-deficient livers." (PMID 37174657, 2023). "We wondered whether ICAM-1+ tumor cell and neutrophil binding is also dependent on CD11b." (PMID 37345070, 2023). "Therefore, we expect that ICAM-1+ tumor cells may secrete specific chemoattractants to recruit neutrophils, which then facilitate their binding with neutrophils." (PMID 37345070, 2023). "On the other hand, ICAM1 may have a role in tumor metastasis." (PMID 37671167, 2023). "Accordingly, tumor cells were extracted for subpopulation analysis, and the identified malignant cells clustered into eleven subclones: BRCA_SRGN, BRCA_SLC39A6, BRCA_ITGB3, BRCA_PECAM1, BRCA_PPP1R1B, BRCA_VCAM1, BRCA_ICAM1, BRCA_S100A9, BRCA_GLUL, BRCA_TASTD2 and BRCA_AGR3." (PMID 37626402, 2023). "Depending on the context, ICAM-1 can either benefit a cancer—for example, by facilitating the clustering of circulating tumor cells or acting in pro-tumorigenic signaling pathways—or it can benefit host survival by facilitating the recognition and destruction of tumor cells by the immune system." (PMID 37237555, 2023).
tumor (continued). "Interestingly, CAR T cells can induce ICAM-1 expression in tumor cells, a feedforward loop that may aid in the destruction of the tumor cells." (PMID 37237555, 2023). "Thus, we speculated whether the low expression of ICAM1 altered the tumor microenvironment in TNBC patients." (PMID 37671167, 2023). "However, ICAM-1 plays diverse roles in anti-tumor responses and immunity, therefore, the targeting treatments of ICAM-1 may be difficult." (PMID 36505809, 2022). "Additionally, researchers were able to show that, despite the weak expression of ICAM-1 by tumor cells, the presence of adequately high numbers of CAR-T cells can upregulate the expression of ICAM-1 via increased IFN-γ production, rendering tumors more permissive to effector T-cell infiltration." (PMID 35466279, 2022). "However, our studies also demonstrate that the transcription factor Fra-2 is able to control the expression of other adhesion molecules as well (L1-CAM, ICAM-1, CD44, ITGB4, and TSPAN8) and thus allows the tumour cells to adhere to the selectin-deficient endothelium via these adhesion molecules." (PMID 34693476, 2022). "Besides, T-cell vesicles were shown to carry high levels of lymphocyte function-associated antigen-1 (LFA-1), which mediates the targeting of tumor sites via binding to intercellular adhesion molecule-1 (ICAM-1) highly expressed on tumor cells and inflamed endothelium." (PMID 35874757, 2022). "Furthermore, CM coculture induced tumor-expressed ICAM1 in dose- and time-dependent manners." (PMID 36264639, 2022). "Furthermore, the rise of sICAM-1 may be attributable to the complex pathogenesis and survival of the tumor, since ICAM-1 is considered to be of great significance in terms of tumorigenesis." (PMID 35740491, 2022). "The importance of ICAM-1 expression by the tumor cells was further highlighted by the fact that EGFR-expressing tumor cells at the center of the tumor islets that weakly expressed ICAM-1 were not able to promote EGFR CAR-T cell activation “arrest” within the tumor islets." (PMID 35466279, 2022). "Moreover, it interferes with the infiltration and delivery of functional T cells towards the tumor, downregulates the expression of intercellular adhesion molecule-1 (ICAM-1) and vascular cell adhesion molecule-1 (VCAM-1), and develops the loss of antitumor immunity and immunotherapeutic resistance." (PMID 36686754, 2022). "Indeed, treatment with the ICAM1 inhibitor, A205804, sensitized tumor cells to DTX." (PMID 36264639, 2022). "However, sICAM-1, as a competitive inhibitor of ICAM-1, can competitively bind to the LFA-1 ligand, inhibit the formation of the ICAM-1/LFA-1 complex, weaken its killing effect, and cause tumor cells to evade the body’s immune surveillance, resulting in tumor development and metastasis." (PMID 34386034, 2021). "However, treatment with anti‐platelet antibody R300 markedly slowed tumor growth compared with that with C301 after insufficient RFA, and treatment with ICAM‐1 antibody could also slow tumor growth." (PMID 33643788, 2021). "Downregulation of MHC I (Major histocompatibility complex I), MHC II, and ICAM1 (intercellular adhesion molecule) in tumor endothelial cells suggests that the antigen presentation and homing abilities of immune cells are decreased, thereby promoting tumor immune tolerance." (PMID 34895349, 2021). "Furthermore, capillarized LSECs release proinflammatory molecules such as cytokines (IL-8 and MCP1) and express adhesion molecules (VCAM-1, ICAM-1, and E-selectin) that act as angiocrine factors supporting the immunosuppressive microenvironment and tumor development." (PMID 35008212, 2021). "Since we have previously shown that CD44 mediates cell aggregation via intercellular interaction, we utilized multiple experimental approaches to test whether ICAM1 also forms homophilic dimers from neighboring cells, thereby resulting in tumor cell aggregation." (PMID 34381029, 2021).
tumor (continued). "However, to access DCs and tumor antigens, CD8+ T cells may rely on intercellular adhesion molecule-1 (ICAM-1) to facilitate tumor infiltration." (PMID 34681719, 2021). "ICAM1 inhibition could suppresses tumor growth and metastasis." (PMID 34176789, 2021). "Based on single-cell RNA sequencing profiles of primary tumor cells and lung metastases of the PDXs, we identified a subpopulation of lung metastatic cells with ~20-fold higher expression of intercellular adhesion molecule 1 (ICAM1, CD54), compared to that of primary tumor cells." (PMID 34381029, 2021). "Although the clinical activity as single agent is modest, it has been shown that anti-angiogenic drugs could normalize the tumor vasculature and increase T cell infiltration by inducing the upregulation of the leukocyte adhesion molecules such as ICAM-1 and VCAM-1 on tumor endothelial cells." (PMID 34956912, 2021). "Extravasation into the tumor tissue is dependent upon interactions with adhesion molecules expressed on the immune cells themselves and the luminal surface of the tumors’ endothelial lining such as E-cadherin, intercellular adhesion molecule-1 (ICAM-1) and vascular cell adhesion molecule-1 (VCAM-1)." (PMID 33121034, 2020). "Finally, ICAM-1 expression had previously been shown to be upregulated after gamma irradiation of human multiple myeloma cells, potentially leading to an increase in the immunogenicity of tumour cells." (PMID 32135474, 2020). "Moreover, different ICAM-1 N-glycoforms may regulate tumor burden and inflammatory signaling, and that the degree of ICAM-1 N-glycosylation can change depending on the cell in which it is expressed." (PMID 32208424, 2020). "Expression of ICAM-1 is further increased in metastases of the liver, where it mediates the formation of a pro-metastatic niche by endothelial cell activation of signalling pathways, assisting tumour cell extravasation, and the recruitment of immune cell populations." (PMID 32135474, 2020). "Besides providing chemoattractants to attract T cells, radiotherapy also accelerates their homing into the tumor bed by increasing the expression of adhesion molecules, such as ICAM-1, on the tumor vasculature endothelium, promoting leucocyte endothelial transmigration." (PMID 33123161, 2020). "Since ICAM-1, which can promote tumor cell/T-cell interaction and T-cell activation, is highly expressed on EWS-FLI1 low cells, we hypothesized that EWS-FLI1 low cells would be more susceptible to T-cell mediated tumor cell apoptosis as compared to cells with high EWS-FLI1." (PMID 31164960, 2019). "Interestingly, LFA-1 blockade and to a lesser extent ICAM-1 blockade caused a decrease in T cell IFNγ production in mixed tumor/T cell cultures but did not affect the level of T cell infiltration into the tumor." (PMID 31231358, 2019). "Furthermore, the local environment generated by LSEC ICAM-1/tumor LFA-1 binding may directly contribute to HSCs activation." (PMID 31511625, 2019). "In addition, ICAM-1 participates in tumor cell adhesion and transendothelial migration." (PMID 31835465, 2019). "This study demonstrated that tumor tissue cells harvested from PCa patients exhibited high NANOG expression and low ICAM1 expression, and PCa patients expressing low levels of ICAM1 had a higher risk of recurrence than those expressing high levels of ICAM1 after surgical cancer resection." (PMID 31619256, 2019). "In addition, given that LFA-1 blockade but not ICAM-1 deficiency/blockade affected the anti-tumor efficacy of adoptive T cell therapy, LFA-1 interactions with other ligands such as ICAM-2 seem to be sufficient to preserve T cell effector function." (PMID 31231358, 2019). "This heterotypic clustering mechanism could be reversed by blocking ICAM1 on vessels or tumor cells, however, endothelial-specific ICAM1 blockade was much more potent, suggesting that ICAM1 enables tumor cell attachment through both direct and indirect mechanisms." (PMID 31497019, 2019).
tumor (continued). "Since tumor cell secretion of soluble ICAM-1, if present, could diminish direct T-cell:tumor cell interaction and thus decrease T-cell mediated tumor cell apoptosis, we tested whether sICAM-1 could be responsible for the decreased T-cell mediated apoptosis we observed in the EWS-FLI1 low cells." (PMID 31164960, 2019). "It has been proposed that ICAM1 has an important function in antitumor immunity by being functionally involved in T cell priming by antigen-presenting cells, trans-endothelial trafficking of effector cells, and facilitating lymphocyte adhesion with tumor cells." (PMID 30082828, 2018). "Notably, despite having higher ICAM-1, we found that EWS-FLI1 ‘low’ cells are actually less susceptible to T-cell mediated apoptosis that EWS-FLI1 ‘high’ cells, suggesting that EWS-FLI1 ‘low’ cells possess an ability to evade T-cell- mediated tumor killing." (PMID 30400822, 2018). "We hypothesized that a bispecific composed of an anti-effector (e.g., anti-LRP6) antibody and an antibody binding to a guide antigen (e.g., a tumor-associated cell surface molecule such as ALCAM, EphA2 or ICAM-1) will modulate potency and cell type selectivity of the anti-effector antibody." (PMID 29335534, 2018). "Therefore, since LFA-1/ICAM-1 T cell aggregation seems to limit T-cell recirculation, transient local blockade of these functions offers opportunity to attain systemic bio-distribution of tumor-reactive T-lymphocytes." (PMID 30258446, 2018). "However, using TGFβ2 and ICAM-1, we could recapitulate the immunosuppressive microenvironment of the tumor, diminishing 50% of perforin expression on naïve CD8+ T cells." (PMID 29966014, 2018). "Similarly, other authors have shown that ICAM-1 expression in mesothelial cells was increased by pre-incubation with TNF-α or IL-6, with a concurrent increase in tumour adhesion, which was then partially attenuated by the use of a monoclonal antibody against ICAM-1." (PMID 29772648, 2018). "To prove whether the effect of PT on ICAM-1 or VCAM-1 expression plays a role in the PT-evoked tumor cell adhesion, we performed a cell adhesion assay, in which endothelial ICAM-1 or VCAM-1 was blocked after PT treatment by a neutralizing antibody before the (untreated) tumor cells were added." (PMID 29100413, 2017). "Based on our results, one can speculate that ICAM-1 acts as a central hub that coordinates a signaling loop between acto-myosin contractility and matrix stiffening that sustains the onset of a proinvasive tumor microenvironment." (PMID 27901489, 2017). "Thus, targeting stromal ICAM-1 might constitute a possible therapeutic mean to counteract tumor cell invasion and dissemination." (PMID 27901489, 2017). "Furthermore, we investigated whether TRAF4/NOX complex-mediated endosomal ROS promotes secretion of soluble ICAM1 (sICAM1) to enhance tumor progression." (PMID 28827764, 2017). "Other potential mechanisms by which ICAM-1 could retard tumor cell metastasis have been proposed." (PMID 29099772, 2017). "Therefore our data suggest that inhibition of membrane-bound ICAM-1 function using ICAM-1 specific blocking antibodies might constitute an interesting possibility to counteract tumor cell invasion and dissemination." (PMID 27901489, 2017). "Therefore, the glycosylation defect of ICAM-1 might be involved in the inhibition of tumor cell extravasation in PKN3 KO mice." (PMID 26742562, 2016). "We therefore examined whether ICAM-1 was overexpressed in the stem-like component of tumor cells." (PMID 27851822, 2016). "Because cancer cells usually produce an elevated number of fibrinogen receptors (eg α5β1, αvβ3 integrins and the ICAM-1 molecule), some scholars have proposed that fibrinogen may facilitate tumor and host cell interactions, thus facilitating tumor cell metastasis." (PMID 27418164, 2016). "Moreover, elevated ICAM-1 levels in patients with advanced stage disease may represent an increased host immune response to tumor cells or simply reflect a larger tumor burden." (PMID 27563824, 2016).
tumor (continued). "Tumor-specific expression of ICAM1 alternative splice variants was not previously reported." (PMID 28105922, 2016). "In addition, ESM1 regulates the lymphocyte function-associated antigen-1 (LFA-1)/intercellular adhesion molecule-1 (ICAM-1) pathway; thus, it may play an important role in the migration of leukocytes into tumor tissues." (PMID 27683113, 2016). "Importantly, the positive effects of SeGP65 were also maintained in mice with mature tumors, i.e., 3 weeks of tumor growth, when ICAM-1 mRNA levels were still elevated within most treatment groups and SeGP65 fed mice alone showed no change with tumor cell infusion." (PMID 26706037, 2016). "Furthermore, we found that ICAM1 can be induced in vivo to promote tumor growth." (PMID 25879517, 2015). "The intercellular adhesion molecule 1 (ICAM-1), a glycoprotein consisting of five extracellular immunoglobulin-like domains, a transmembrane and a C-terminal intracellular domain, plays an important role in tumor immune surveillance and elimination of neoplastic cells." (PMID 26513172, 2015). "Thus, we further explored whether ICAM1 is induced in vivo and if so, how ICAM1 expression affects tumor growth." (PMID 25879517, 2015). "ICAM-1 may be involved in tumor suppression through an immuno-surveillance mechanism." (PMID 24742333, 2014). "Additionally, tumor cells are capable of attaching to leukocytes by expressing ICAM-1." (PMID 25275457, 2014). "ICAM-1 has also shown to be upregulated in human multiple myeloma cell lines and primary tumor cells following exposure to high-doses of irradiation and facilitates T cell infiltration into tumors and itself, may be presented as an antigenic protein on the surface of tumor cells." (PMID 24434638, 2014). "Moreover, the LFA-1/ICAM-1 interaction induces the necessary cytokine release for the termination of tumor growth while lymphocytes interact with tumor cells; however, tumor cells with higher level of cell adhesion molecules are observed to form metastatic lesions." (PMID 25032811, 2014). "Moreover, WISP-1 and ICAM-1 expression correlated with the tumor stage of patients with OSCC." (PMID 24205072, 2013). "Analogous to the effect of sMICA on NK-cell function, it is possible that the secretion of sICAM-1 by human tumours may hinder the interaction between ICAM-1 and CD11b/CD18, leading to the downregulation of CD11b expression on NK cells and thereby affecting the TINK-cell functional maturation." (PMID 23565296, 2013). "Thus, we hypothesise that the secretion of sICAM-1 by human tumours may hinder the interaction between ICAM-1 and CD11b/CD18, leading to the downregulation of CD11b expression on NK cells and thereby resulting in the DN NK-cell accumulation." (PMID 23565296, 2013). "One can hypothesize that comparative downregulation of KDR (and perhaps, angiogenesis in general) in the primary tumor might impart selection pressure for invasion leading to upregulation of ICAM1 that reflects a tumor's potential to establish a metastatic lesion in a draining lymph node." (PMID 16780590, 2006). "ICAM-1 expression was increased in 8/8 cell lines treated with the de novo methyltransferase inhibitor 5-aza-2′-deoxycytidine, indicating that methylation of CpG islands may play a role in the down-regulation of its expression in primary tumours." (PMID 11720474, 2001). "Our analysis reveals a dual role of T cell-macrophage crosstalk: CD4+ and CD8+ exhausted T cells drive anti-tumor M1-like TAMs activation via TNF-TNFRSF1A, TNFSF14-LTBR, and ICAM1-ITGAL/ITGB2." (PMID 42001468, 2026). "Another circRNA, hsa_circ_0007456, binds to miR-6852-3p to regulate intercellular adhesion molecule-1 (ICAM-1) expression, increasing NK cell-mediated cytotoxicity against HCC cells and inhibiting tumor development." (PMID 41602547, 2026). "For T cell–tumour cell interactions, we observed several adhesion interactions, including between CD58 and CD2 and between ICAM1 and ITGAL." (PMID 41261135, 2026).